MSLN (mesothelin)
Diseases named in the same sentence as MSLN in open-access papers (continued):
Sharing a sentence is not in itself a finding about the gene and the disease.
mesothelioma (continued). "In one study, the maytansinoid tubulin inhibitor, DM4, was targeted to mesothelioma, pancreatic, and ovarian tumors overexpressing mesothelin by conjugation to an anti-mesothelin antibody via a disulfide-containing linker." (PMID 34361141, 2021). "We initially hypothesized that ERC/mesothelin influences the morphology of mesothelioma, because its expression correlated well with morphological subtypes of mesothelioma." (PMID 32677949, 2020). "Currently, CARs that target human epidermal growth factor 2 (HER2) and epidermal growth factor receptor variant III (EGFRvIII) against glioblastoma, GD2 disialoganglioside against neuroblastoma, and mesothelin (MSLN) against mesothelioma, are being evaluated in clinical trials." (PMID 32849635, 2020). "The paucity of effective therapies for mesothelioma, including the limited success of mesothelin targeted therapy, immune checkpoint blockade, anti-angiogenesis therapies, and neoantigen based vaccines, necessitate the development of additional therapeutic strategies." (PMID 32903438, 2020). "We hypothesized that the expression status of ERC/mesothelin influences the morphological phenotype of mesothelioma." (PMID 32677949, 2020). "We hypothesized that ERC/mesothelin expression influences the histological differentiation of mesothelioma, and tested this hypothesis." (PMID 32677949, 2020). "We hypothesized that the expression of ERC/mesothelin influences the morphology of cells, as its expression is well correlated to the histological subtypes of mesothelioma." (PMID 32677949, 2020). "Consequently, ERC/mesothelin expression and the histological subtype of mesothelioma are well correlated." (PMID 32677949, 2020). "Mesothelin and fibroblast activation protein are the two identified TAAs in mesothelioma and malignant pleural mesothelioma, in which mesothelin is a widely studied antigen in IVT mRNA CAR T. Colon cancer is a type of malignant tumor occurring in the inner wall of the large intestine." (PMID 32899932, 2020). "Many solid tumors also express MSLN, including mesothelioma and pancreatic adenocarcinoma." (PMID 32605175, 2020). "Interestingly, in a study using mesothelioma markers in cytological specimens, it was concluded that calretinin was a better marker than mesothelin." (PMID 30965570, 2019). "Mesothelin: Mesothelin is a cell surface glycoprotein and differentiation marker highly expressed in mesothelial cells lining the pleura, pericardium, and peritoneum, and in several human cancers, such as mesotheliomas and adenocarcinomas." (PMID 30965570, 2019). "When introducing this MSLN promoter element upstream of the large T antigen gene in the transgenic MexTAg mouse model, the promoter becomes active in asbestos-exposed mesothelial cells, leading to asbestos-induced mesotheliomas." (PMID 30555628, 2018). "Since local invasion is the characteristic clinical feature of MM, and mesothelin, another typical marker of mesothelioma, increases migration and invasion in MM cells, the effect of CR overexpression on cell migration/proliferation and invasion was investigated." (PMID 30555628, 2018). "Interestingly, this approach identified already known mesothelioma genes, BAP1 and NF2 being downregulated, and MSLN, which encodes mesothelin, upregulated in MPM in comparison with MH." (PMID 30060470, 2018). "Altogether, this study shows that the local administration of anti-mesothelin immunotoxins potentiates the effect of anti-CTLA-4 in a murine mesothelioma model and induces markers of immunogenic cell death, providing preclinical support to pursue this combination strategy in the clinic." (PMID 30441807, 2018). "The poor sensitivity of mesothelin thus had a limited value for early diagnosis of mesothelioma." (PMID 28335760, 2017). "In addition, we validated the statistical deregulation of 66 genes out of the selected 117, among which there were several well-known mesothelioma genes, such as MSLN, BAP1, and NF2." (PMID 27835874, 2017).
mesothelioma (continued). "Mesothelin immunohistochemistry may assist the differential diagnosis of thymoma vs. thymic carcinoma as well as prognostication of mesothelioma patients." (PMID 28460459, 2017). "In this study, we evaluated whether anti-MSLN BsAbs could be used to specifically deliver drug-loaded EDVs to mesothelioma and suppress tumour growth in mesothelioma xenografts." (PMID 29059207, 2017). "Because of its importance in EMT and CSC regulation, MSLN could be a potential therapeutic target for advanced and recurrent lung cancer and mesothelioma." (PMID 28288645, 2017). "We further investigated possible diagnostic values of mesothelin and midkine using ROC curve analyses to differentiate mesothelioma from non-mesothelioma patients." (PMID 28335760, 2017). "Serum mesothelin levels were significantly higher in the patients with mesothelioma than in those with metastatic cancers to pleura, benign asbestos pleurisy, benign pleural diseases or pleural diseases other than mesothelioma." (PMID 28335760, 2017). "Serum mesothelin levels have been found to correlate with mesothelioma responsiveness to anti-mesothelin therapies, however, it has not been shown whether immunohistochemistry can be used as a biomarker to predict clinical response to these drugs." (PMID 28460459, 2017). "MSLN is overexpressed in a broad spectrum of solid tumors including mesothelioma and lung cancer." (PMID 29100432, 2017). "The role of MSLN in tumor formation and metastasis of lung cancer and mesothelioma or any role in EMT and cancer stem cell (CSC) regulation is largely unknown." (PMID 28288645, 2017). "Mesothelin was regarded as a biomarker for differential diagnosis of mesothelioma." (PMID 28335760, 2017). "In mesothelioma cells, we present that knockdown of MSLN reversed the EMT to MET phenotype and significantly reduced CSC markers and ALDH activity, which may contribute to the observed reduction in tumorigenicity and metastasis of the knockdown cells." (PMID 28288645, 2017). "Favorable interaction between combinations of mesothelin-targeted immunotoxin and taxanes has also been previously reported for triple negative breast, gastric, lung, mesothelioma (Zhang and Hassan, unpublished observation) and mesothelin-transfected epidermoid cancer cells grown in mouse models." (PMID 27999204, 2017). "If successful, NIR-PIT in mesothelin expressing, unresectable tumors such as mesothelioma and pancreatic cancer, could have a meaningful impact on the survival of such patients." (PMID 26981775, 2016). "The new assay can also be used to measure serum mesothelin concentration in mesothelioma patients, indicating its potential use for monitoring patients treated with current antibody therapies targeting Region I. The antibodies are highly specific and sensitive in immunostaining of mesothelioma." (PMID 25996440, 2015). "The assay can be used to detect mesothelin in mesothelioma patient sera." (PMID 25996440, 2015). "Mesothelin is an emerging cell surface target in mesothelioma and other solid tumors." (PMID 25996440, 2015). "Mesothelin has been used as a tissue marker for mesothelioma and other cancers." (PMID 25996440, 2015). "However, the most extensively studied is mesothelin, which has been shown to potentially differentiate between mesothelioma and other conditions, both benign and malignant, and also potentially correlates with response to therapy." (PMID 25227779, 2014). "ERC/mesothelin is expressed in mesothelioma and other malignancies." (PMID 24146039, 2014). "In addition, some studies also reported elevated levels of soluble MSLN in mesothelioma, ovarian cancer and pancreatic cancer." (PMID 24520352, 2014). "In mesothelioma MSLN promotes tumor cell invasion by increased MMP-9 secretion." (PMID 25506917, 2014). "Furthermore, while hyaluronan is produced by all phenotypes of mesothelioma, elevated mesothelin levels are mostly seen in epithelioid and mixed phenotypes." (PMID 23991032, 2013).
mesothelioma (continued). "Monoclonal antibodies against mesothelin are being evaluated for the treatment of mesothelioma." (PMID 24260587, 2013). "In contrast, the diagnostic utility of pleural effusion and serum mesothelin was limited to mesothelioma but not non-mesothelioma MPEs." (PMID 23009708, 2012). "Subjects with mesothelioma, in comparison to subjects with benign effusions, had significantly higher pleural fluid mesothelin (median 38 nM vs. 4.6 nM, p<0.001) and serum mesothelin levels (median, 2.0 nM vs. 1.0 nM, p<0.001)." (PMID 23009708, 2012). "Despite the higher fraction of mesothelioma lines positive for MSLN, it was also detected at high levels in 2 lung cancer lines and 3 other unrelated cancer lines derived from papillotubular adenocarcinoma, signet ring carcinoma and transitional cell carcinoma." (PMID 21984916, 2011). "Interestingly MSLN levels appear to be upregulated in the mesothelioma lines compared to the primary mesothelial cells, while LRRN4 and UPK3B, are either lost or down-regulated." (PMID 21984916, 2011). "MUC16 has been previously demonstrated to be important in the metastasis of solid tumors to the central nervous system via its interaction with mesothelin, a protein differentially expressed in normal mesothelial cells, mesotheliomas and some other mesenchymal malignancies." (PMID 22066010, 2011). "For biphasic mesothelioma, which contains both epithelioid and sarcomatoid components, MSLN expression exhibits regional heterogeneity: epithelioid regions generally maintain robust MSLN positivity, whereas sarcomatoid regions are predominantly negative or weakly positive." (PMID 41400642, 2025). "Consequently, the overall MSLN expression level in biphasic mesothelioma typically falls between that of epithelioid and sarcomatoid subtypes, with the specific expression pattern potentially determined by the proportion and distribution of these two components within the tumor." (PMID 41400642, 2025). "In addition, UPK3B and MSLN are significantly positively correlated with mesothelioma E-score." (PMID 36467966, 2022). "Thus, for early diagnosis it will also be necessary to validate GAS5 as well as the previously identified RP1-86D1.3 in a prospective study regarding their potential to detect mesothelioma in prediagnostic plasma samples and to complement calretinin and mesothelin." (PMID 32435497, 2020). "SS1P is an anti-mesothelin immunotoxin composed of a targeting antibody fragment genetically fused to a truncated fragment of Pseudomonas exotoxin A. Delayed responses reported in mesothelioma patients receiving SS1P suggest that anti-tumor immunity is induced." (PMID 30441807, 2018). "The TAA mesothelin (MSLN) is highly expressed in several solid cancer types, particularly in EOC, PDAC, and mesothelioma." (PMID 40402266, 2025). "Mesothelin is expressed in the majority of epithelioid mesothelioma cases, whereas WT1 is expressed in both epithelioid (70%–100%) and sarcomatoid (10%–45%) mesothelioma." (PMID 40918456, 2025). "Ongoing exploration of novel or optimized targets includes B7-H3 and GD2 for brain cancer, MSLN and CEA for pancreatic cancer, MSLN and FAP for mesothelioma, and GPC3 for liver cancer." (PMID 40969260, 2025). "Mesothelin (MSLN) is a 40-kDa glycoprotein, originally believed to be produced solely by mesothelioma cells; however, later investigations revealed its expression in numerous normal human tissues." (PMID 40362535, 2025). "The in vitro antitumor response of TC-210 and TC-210 + PD1-CD28 CSRs was assessed using the mesothelioma cell line, MSTO-211H, engineered to express human MSLN (MSTOMSLN) or MSLN and PD-L1 (MSTOMSLN-PD-L1)." (PMID 37848682, 2023). "In a phase 1 investigation, an anti-mesothelin-specific ADC called anetumab ravtansine was found to have promising antitumor efficacy and a tolerable safety record in mesothelioma patients who had already received treatment." (PMID 37469419, 2023).
mesothelioma (continued). "The specific mesothelin TTC, BAY 2287411 in mesothelioma, ovarian, and breast cancers, among others, showed anti-tumor potency both in vitro and in vivo in PDX models." (PMID 35326701, 2022). "Mesothelin (MSLN) is a cell surface glycoprotein that was originally found to be expressed on normal mesothelial cells and mesothelioma." (PMID 35692779, 2022). "CRS-207, a live attenuated form of Listeria monocytogenes engineered to express human mesothelin, stimulated a tumour-specific CD8+ T cell response in 60% of subjects with advanced cancer, including two patients with mesothelioma." (PMID 34226685, 2021). "Accordingly, in this study we developed novel HSV-1 based oncolytic viruses targeting mesothelin, a TAA frequently expressed in triple-negative breast cancer, as well as in additional neoplasms, including the orphan disease mesothelioma." (PMID 33418877, 2021). "Another ADC with potent anti-mesothelioma activity, αMSLN-MMAE, is a humanised anti-mesothelin mAb conjugated to the microtubule-disrupting drug monomethyl auristatin A (MMAE) with a lysosomal-protease-cleavable valine–citrulline linker." (PMID 34226685, 2021). "They concluded that there is a biological role for MSLN as a factor-promoting tumor invasion and MMP-9 expression in MSLN-expressing mesothelioma tissue." (PMID 34572485, 2021). "Mesothelin (MSLN), Wilm’s tumor protein WT1 and YAP1, which are well-known tumor markers in mesothelioma cells, have been applied as therapeutic targets and prognostic indicators." (PMID 34768716, 2021). "They injected mesothelioma tumor cell lines into the flanks of NSG mice and treated the mice with anti-mesothelin second generation CAR-T cells." (PMID 32325898, 2020). "To date, MSLN has been utilized as a target of CAR T cells against solid cancers, including mesothelioma, lung cancer, breast cancer, and pancreas cancer." (PMID 30777106, 2019). "We also assessed the consequences of genetically altered MSLN levels on EMT, the malignant phenotype, and stem properties of human lung carcinoma and mesothelioma cells." (PMID 28288645, 2017). "Firstly, MSLN was found to be highly upregulated in non-small cell lung cancer (NSCLC) patient tissues and in lung carcinoma and mesothelioma cell lines." (PMID 28288645, 2017). "MSLN plays a key role in controlling epithelial-to-mesenchymal transition (EMT) and stem properties of human lung cancer and mesothelioma cells that control their tumorigenicity and metastatic potential." (PMID 28288645, 2017). "Flow cytometric analysis of ALDH activity by Aldefluor® assay revealed that knockdown of MSLN significantly reduced the ALDH activity of lung carcinoma (H460) and mesothelioma (H2052) cells." (PMID 28288645, 2017). "NCI-H226 cells were incubated with JMAM mAbs followed by staining with existing Abs already known to bind to mesothelioma [anti-calretinin, anti-podoplanin (D2-40), anti-GLUT-1, anti-CD25 (BC96), anti-CD26 (1F7, 5F8), anti-C-ERC/mesothelin (22A31)]." (PMID 27342200, 2016). "Antibodies against Podoplanin, Mesothelin, EMA, and GLUT-1 stained cell-block specimens, which confirmed these atypical cells as derived from mesothelioma." (PMID 27342200, 2016). "N-ERC/mesothelin is a 31-kDa protein that forms the N-terminal fragment of the full-length 71-kDa ERC/mesothelin protein and is secreted into the blood of mesothelioma patients." (PMID 25347530, 2014). "However, mesothelin as an individual biomarker is characterized by a high specificity of 89% (95% CI 86; 91%) but a relatively low sensitivity of 58% (95% CI 54; 62%) for the discrimination of mesothelioma patients and asbestos exposed subjects as recently shown in a meta-analysis." (PMID 25469901, 2014). "Excluding sarcomatoid mesothelioma from analysis revealed a median mesothelin concentration of 2.03 nmol/l (IQR 1.24–5.82 nmol/l) and a median miR-103a-3p value of 228.5 (IQR 144.2–608.5) for mesothelioma patients." (PMID 25469901, 2014).
mesothelioma (continued). "In mesothelioma, the TAA's mesothelin and Wilms tumour-1 (WT-1) are highly expressed and thought to be physiologically relevant to this tumour type." (PMID 22778767, 2012). "The expression of general mesothelioma markers (mesothelin, cytokeratin 5/6, calretinin, HBME-1, thrombomodulin, and WT-1) in spheroids is consistent with those of mesothelioma specimens." (PMID 22737246, 2012). "Epithelioid-type MPMs were immunostained with antibodies against intelectin-1 or typical mesothelioma markers, such as calretinin, CK5/6, podoplanin, WT-1, and mesothelin." (PMID 22768319, 2012). "Histological pictures of normal parietal samples and biphasic mesothelioma stained with VG5Q, Thymidylate Synthase, and Mesothelin antibodies are shown illustrating the expression in normal pleura and the malignant epithelial and sarcomatous components." (PMID 19662092, 2009). "One such strategy involves genetically engineered T cells, known as chimeric antigen receptor T (CAR-T) cells, designed to specifically target MSLN—an antigen found mainly, although not exclusively, in mesothelioma cells." (PMID 40362535, 2025). "Notably, MSLN shedding is a mechanism by which high concentrations of MSLN accumulate in the serum of EOC and mesothelioma." (PMID 40402266, 2025). "In addition, many solid tumors, especially mesothelioma, epithelial ovarian cancer, and PDAC, highly express MSLN, making MSLN a popular target for antibody-based therapeutics." (PMID 38706610, 2024). "Significantly higher mesothelin expression was detected in the effusions from mesotheliomas (mean, 6.99; 95% CI, 5.82–8.40) than those from the non-mesotheliomas (mean, 0.65; 95% CI, 0.55–0.77) (p < 0.001)." (PMID 39315086, 2024). "Canine mesothelin exhibited significantly higher expression in the canine mesotheliomas than in the noncancerous tissues." (PMID 39315086, 2024). "Relative expression levels were compared between mesothelioma and non-mesothelioma (non-MS) tumor tissues using qPCR to analyze mesothelin expression in various tumor types." (PMID 39315086, 2024). "Among the several discovered biomarker candidates, mesothelin, a cell-surface membrane-bound glycophosphatidylinositol (GPI)-anchored protein, is the only molecule approved by the Food and Drug Administration for clinical use in mesothelioma." (PMID 39315086, 2024). "The results demonstrated substantial mesothelin overexpression in the mesotheliomas compared to that in the non-mesothelioma tumors, supporting the mesothelin’s potential diagnostic usefulness in canine mesotheliomas." (PMID 39315086, 2024). "coli K-12 DH5α engineered to display human DR18 potently activated mesothelin-targeting CAR NK cells and safely enhanced their trafficking into the tumors, leading to improved control and survival in xenograft mice bearing mesothelioma tumor cells, otherwise resistant to NK cells." (PMID 38562821, 2024). "Tumours of approximately equal size arising in lenti-Cre induced mice with and without asbestos were compared by IHC for expression of cell lineage markers (pan-cytokeratin, vimentin and smooth muscle actin) along with Ki67 and the commonly used mesothelioma markers WT1 and Mesothelin." (PMID 37441092, 2023). "Mesothelin (MSLN) is a glycoprotein expressed in the mesothelial cells of the pleura, peritoneum, and pericardium and it is reported to be highly expressed in several types of malignant tumors, including mesothelioma." (PMID 37445594, 2023). "Patients with mesothelin-positive cancers: ovarian, pancreatic, mesothelioma, non-small cell lung cancer." (PMID 36268019, 2022). "In terms of outcome measures, in absence of stronger biomarkers of mesothelioma therapeutic efficacy, we decided to consider serum mesothelin levels (primary outcome) and the miRNA expression profile (secondary outcome)." (PMID 35987988, 2022). "Mesothelin is a 40-kDa cell surface glycoprotein expressed by all epithelioid, but not by sarcomatoid or the spindle component of biphasic mesotheliomas." (PMID 34226685, 2021).